ENSG00000251357 (novel protein)
Gene: Protein-coding gene on chromosome 22 (23,862,188 to 23,895,223, forward strand). Ensembl gene ENSG00000251357.
Genetic constraint (gnomAD): Loss-of-function variants: 29 observed, 22.41 expected, observed/expected ratio (o/e) 1.29, 90% interval 0.96 to 1.74. Missense variants: 293 observed, 248.31 expected, observed/expected ratio (o/e) 1.18, 90% interval 1.07 to 1.3. Synonymous variants: 126 observed, 109.16 expected, observed/expected ratio (o/e) 1.15, 90% interval 1 to 1.34.